ERBB2 (erb-b2 receptor tyrosine kinase 2)
Diseases named in the same sentence as ERBB2 in open-access papers (continued):
Sharing a sentence is not in itself a finding about the gene and the disease.
tumor (continued). "Further support for the use of scFv(FRP5)-ETA in tumor therapy arose from a study investigating intratumoral injection of the antibody toxin in patients with dermal metastases of ErbB2-expressing tumors." (PMID 16168106, 2005). "Thereby immunological memory was induced, leading to long-term systemic immunity in the tumour-free animals and complete protection, several months later, against subsequent re-challenge with intravenously injected Renca-lacZ/ErbB2 cells." (PMID 15812545, 2005). "Vaccination with Tc-ErbB2/Th-HA liposomes was even more effective, resulting in complete protection of all five mice in this group from outgrowth of Renca-lacZ/ErbB2 tumours." (PMID 15812545, 2005). "In a subset of patients with ErbB-2 overexpressing tumours, we demonstrated that P-Akt levels are of particular prognostic significance." (PMID 15987444, 2005). "ScFv(FRP5)-ETA is a recombinant single-chain antibody toxin with binding specificity for ErbB2-overexpressing tumor cells." (PMID 16168106, 2005). "Upon formation of palpable tumours (day 2 post tumour cell injection), animals were treated by s.c. injection of Tc-ErbB2 or Tc-ErbB2/Th-HA liposomes corresponding to 7.5 μg of coupled ErbB2 Tc peptide into the vicinity of each tumour." (PMID 15812545, 2005). "Potent antitumoral activity of scFv(FRP5)-ETA against ErbB2-overexpressing tumor cells was previously demonstrated in vitro and in animal models." (PMID 16168106, 2005). "High levels of phosphorylated Akt correlated (P < 0.01) with poor prognosis, and the significance of this correlation increased (P < 0.001) in the subset of patients with ErbB-2 overexpressing tumours." (PMID 15987444, 2005). "The influence of liposomal vaccine constructs on the growth of established tumours was investigated in animals carrying Renca-lacZ/ErbB2 tumours." (PMID 15812545, 2005). "Of note, the critical role of helper T cells for the activation of tumour-specific CTLs has also become apparent in recent studies with regular ErbB2 peptide vaccines." (PMID 15812545, 2005). "Immunohistochemical studies showed cytoplasmic P-Akt and P-MAPK expression in tumor cells with erbB2 and erbB3 co-expression, predominantly a perivascular distribution." (PMID 16168116, 2005). "Upon binding of BIg5 to ErbB2 on tumor cells, these cells display CD86 on their surface and thus can deliver costimulatory signals for T-cell activation." (PMID 15242515, 2004). "Possibly, ERBB2 overexpression in tumours with such molecular background is a minor additional alteration in terms of cell response to chemotherapy." (PMID 15545967, 2004). "Rejection of ErbB2+ tumors led to long-term protection also against subsequent challenge with intravenously injected ErbB2- tumor cells." (PMID 15242515, 2004). "In this respect, it has been reported that a combination of the EGFR-directed mAb C225 and the erbB2 directed mAb 4D5 or using dual EGFR/HER2 inhibitors inhibited proliferation of tumor cell lines more strongly than either mAb alone." (PMID 15305194, 2004). "Inoculation of these bystander cells close to subcutaneously growing Renca-lacZ/ErbB2 tumors should provide a long-lasting source to achieve high local concentrations of BIg5 at the tumor site." (PMID 15242515, 2004). "After binding to ErbB2 on murine Renca-lacZ/ErbB2 tumor cells, about 50% of initially bound BIg5 is still present on the cell surface after 4 hours." (PMID 15242515, 2004). "For example, an analysis of trial outcomes according to HER1 (EGFR) and HER2 (ErbB2) status demonstrated that the difference in the effectiveness of letrozole and tamoxifen was particularly marked for tumours that coexpressed ER and HER1 and/or HER2." (PMID 14710200, 2004).
tumor (continued). "For immunotherapy of ErbB2 expressing tumors, we developed a strategy to supply the tumor cells with costimulatory activity." (PMID 15242515, 2004). "For in vivo studies, Erb-hcAb was tested on murine TUBO tumour cells expressing ErbB2 of rat origin." (PMID 15305184, 2004). "The ErbB family of receptor tyrosine kinases, consisting of the EGF receptor, ErbB2, ErbB3 and ErbB4, directs a broad range of developmental events and contributes to the malignancy of a number of tumour types." (PMID 14735165, 2004). "The common criteria of ERBB2 positivity (2+ and 3+) in tumour tissues were established with reference to ERBB2 expression in normal tissues." (PMID 15545967, 2004). "We have characterised the ERBB2 gene copy number, mRNA and protein levels in the tumour cell lines investigated in this study." (PMID 12942124, 2003). "The last molecule we considered for the detection of tumour contamination is ErbB2, a tyrosine kinase receptor of the EGF receptor family." (PMID 12569382, 2003). "A likely candidate for this factor or mechanism was growth factor/receptor or oncogene de-regulation, as some of the tumours in this study have been found to over-express erbB2, a member of the epidermal growth factor receptor or EGFR family." (PMID 11953859, 2002). "We demonstrated that human lung epithelial cells, overexpressing erbB-2, formed tumours in nude mice only when high levels of transforming growth factor (TGF)-alpha were produced (E6T cells)." (PMID 9569041, 1998). "Overexpression of the epidermal growth factor receptor (EGFR) and ErbB-2 has been observed in a variety of human tumours, making these receptors promising targets for directed tumour therapy." (PMID 8826849, 1996). "Amplification and overexpression of the erbB-2 gene product, being unique to malignancy, confer onto this antibody-mediated therapy high tumour specificity." (PMID 8956788, 1996). "The copy numbers per haploid genome of 11 protooncogenes in every tumour sample were determined: H-ras, K-ras, N-ras, c-myc, N-myc, L-myc, erbB, mos, myb, ncu (erbB-2) and ral amplifications." (PMID 2547415, 1989). "Furthermore, one of the key contributing factors to rapid tumour progression is the overexpression of human epidermal growth factor receptor type-2 (HER-2/ ErbB2)." (PMID 41541222, 2026). "HER2 (ERBB2) is an established oncogenic driver in various tumor entities." (PMID 41535645, 2026). "The tumor harbored two mutations in ERBB2, which encodes HER2." (PMID 41538481, 2026). "Encouraged by the finding that ERBB2 blockade enhances MHC-I induced T cell-mediated killing of SCLC cells, we sought to investigate the impact of ERBB2 and anti-PD-1 on the tumor immune cell compartment applying scRNA-seq in an autochthonous mouse model of SCLC." (PMID 41361170, 2025). "Notably, the expression of ESR1, ERBB2, and Ki67 has been investigated for their correlation with tumor stage and grade." (PMID 40948378, 2025). "This is the first trial to demonstrate sustained responses to HER2-targeted therapy in patients selected based on somatic ERBB2 mutations, regardless of tumor type." (PMID 40828885, 2025). "Importantly, both patients had concurrent alterations in other signaling cascades, such as ERBB2, which likely explain tumor resistance to targeted treatments." (PMID 41357601, 2025).
tumor (continued). "In “targeted, non-tumor” toxicity, T cells target normal tissue cells that express tumor-associated antigens, such as B-cell aplastic anemia observed with CD19 CAR, and pulmonary edema caused by ERBB2 CAR." (PMID 40406483, 2025). "Moreover, in mouse mammary epithelium, the overexpression of c-Myc and ErbB2 is sufficient alone to induce tumor formation." (PMID 40136510, 2025). "Moreover, multiple studies have demonstrated that the degree of ERBB2 amplification as measured by quantitative copy number—a proxy for the degree of HER2 addiction in a tumor—is a predictor of response, with higher copy number associated with better outcomes." (PMID 40178042, 2025). "Immunohistochemistry demonstrated ERBB2 overexpression in>10% of tumor cells." (PMID 41403731, 2025). "Moreover, a tendency for higher CD4+ T cells and CD8+ T cells in tumours harbouring ERBB2 amplification was detected." (PMID 40650126, 2025). "Furthermore, overexpression of the ERBB2 gene is involved in processes such as the dysregulation of iodine metabolism, tumor proliferation, metastasis, and drug resistance." (PMID 40725233, 2025). "HER2 phenotype of BC, also known as ERBB2 or HER2-neu, represented overexpression in tumor cells." (PMID 40080721, 2025). "The results highlight the T-DXd-resistance mediated by ERBB2 i14e in tumor development." (PMID 39948369, 2025). "We compared the prevalence of oncogenic co-alterations in ERBB2mut (excluding samples with ERBB2 co-amplification) versus ERBB2wt (non-mutated and non-amplified) tumors among the five major ERBB2mut tumor types." (PMID 40178042, 2025). "As we identified ERBB2 as a relevant pathway that mediates the expression of MHC-I and thereby antigen presentation in SCLC, we further investigated the impact of ERBB2 expression in SCLC patients with high tumor mutational burden (TMB)." (PMID 41361170, 2025). "The staging of the disease, which is essential for determining the treatment plan, is based on tumour size, lymph node involvement, presence of metastases, and specific biomarkers such as oestrogen receptors, progesterone receptors and the ERBB2 (HER2) receptor." (PMID 41016048, 2025). "z cells could effectively lyse tumor cells expressing ErbB2 in vitro and the retention of specific recognition and anti-tumor activity towards tumor cells in vivo resulted in a reduction in lung metastasis in RCC models." (PMID 40052147, 2025). "ERBB2 dimerization has been shown to activate signaling molecules that regulate tumor metabolism." (PMID 40966256, 2025). "This limited expression pattern suggests that CD155 may have a lower risk of on-target, off-tumor effects when compared with EGFR, ERBB2, and ROR1." (PMID 40478751, 2025). "Additionally, ERBB2 exon 20 and EGFR exon 20 insertion mutations have been associated with an immunosuppressive tumor microenvironment." (PMID 41426315, 2025). "In the United States, the FDA approved ivosidenib for IDH1 mutations and pemigatinib, infigratinib, and futibatinib for FGFR2 fusions, alongside tumor-agnostic treatments for mismatch repair deficiency, NTRK fusions, ERBB2 amplifications, BRAF V600E mutations, and RET fusions." (PMID 39996880, 2025). "However, the relationship between ERBB2 signaling and tumor metabolism in dogs remains poorly understood." (PMID 40966256, 2025). "ERBB2 was significantly more frequent in the Asian group, which aligns with its higher activation in BC within this ethnic group and suggests a potential role of this oncogene’s amplification in tumor aggressiveness." (PMID 40136626, 2025). "For example, recurrent amplification of ERBB2, may contribute to tumour aggressiveness and poor prognosis." (PMID 40813389, 2025).
tumor (continued). "ErbB2-positive tumour cells that also expressed MUC1 were specifically targeted, stimulating an ErbB2-dependent immune activation with increased production of IFN-γ that synergistically promoted a cytotoxic response, although IL-2 secretion was relatively low compared to control CAR-T cells." (PMID 39596267, 2024). "Moreover, our omics analysis of tumours revealed similarities between ERBB2 tumours in humans and those from F1Bx mice at clinical, genomic, expression, and signaling levels." (PMID 39067134, 2024). "Additionally, the eviction from the nucleus or the silencing of isoform c blocked tumor growth, highlighting the dominant oncogenic potential of isoform c and suggesting both canonical and alternative isoforms of ErbB-2 as therapeutic targets in TNBC." (PMID 38473804, 2024). "Interestingly, the ketogenic diet increased tumor size and decreased survival in mice bearing wild-type ErbB2+ tumors, consistent with the efficient use of lipids and ketone bodies as metabolic fuels for NIC/Cpt1a+/+ tumor cells in vitro and in vivo." (PMID 39097623, 2024). "In this retrospective pooled analysis of 3 randomized clinical trials including 1289 patients with ERBB2/HER2-positive EBC, the association between pCR and EFS differed by tumor intrinsic subtype, and the benefit of dual ERBB2/HER2-blockade was limited to ERBB2-enriched tumors." (PMID 38546612, 2024). "Furthermore, this inhibition resulted in enhanced anti-tumour effects of anti-erbB2/neu monoclonal antibody targeted therapy in Balb/c mice having CT26Her2 tumours by inhibiting regulatory T cells function and induction of tumour immunity." (PMID 39703687, 2024). "Our observed localization of kataegis loci close to amplifications was particularly clear for the ER-positive tumor groups but also for ERnHER2p tumors with respect to the 17q12 locus (including ERBB2), although it should be noted that our studied ERnHER2p group is very small." (PMID 38658600, 2024). "In this study, we conducted transcriptomic profiling on 285 tissue samples, pretreatment biopsies (2 per tumor) and residual tumors, from 129 patients, along with ERBB2 FISH and profiling of the immune microenvironment using NanoString digital spatial profiling." (PMID 38300710, 2024). "All independent factors identified in the luminal ERBB2-negative cohort, apart from tumor size, were associated with high nodal burden in ILC also and were included in the lobular prediction model with an AUC of 0.74 (95% CI, 0.66-0.83) in the development set." (PMID 39320882, 2024). "Studies that have compared ERBB2 gene expression between tumors with either dim or incomplete IHC HER2 staining and negative HER2 expression have reported higher mRNA levels of ERBB2, validating the higher presence of this tyrosine kinase receptor within these tumor cells." (PMID 39335113, 2024). "Notably, the somatic NGS panel can offer other information with clinical relevance, such as the presence of mutations in BRCA1, BRCA2, PALB2, ERBB2, and ESR1, in addition to molecular changes that can be treated with tumor-agnostic therapies." (PMID 38952553, 2024). "Unlike other cancer-causing genes, no single prevalent mutant ERBB2 allele has been found, and the distribution of mutations differs depending on the type of tumor." (PMID 39335117, 2024). "When analyzing carcinomas stratified only by the presence of activating mutations in the PI3K-AKT pathway, regardless of the tumor HER2 status, we found that the presence of such a mutation was associated with a lower ERBB2 expression (p = 0.0002)." (PMID 38893129, 2024).
tumor (continued). "Taken together, we have presented here that the engineered destabilized 3'UTR ERBB2-30 delivered by IO nanocages inhibited the drug-resistant EGFR T790M NSCLC with 50% complete tumor lysis, 60% inhibition of ERBB2 protein, 50% therapeutic inhibition of tumor, and 80% reduction of malignant cells." (PMID 38699639, 2024). "The assay integrates biological information tracking immune response, luminal differentiation, tumor cell proliferation and expression of the HER2 17q12-21 chromosomal amplicon, including the ERBB2 gene, with clinical information (i.e., tumor size and nodal status)." (PMID 38653928, 2024). "For patient 32, the post-resistance tumor sample had a clonal ERBB2L869R activating mutation that was also present in the pre-treatment sample, as well as an acquired ERBB2 focal high amplification (copy number above ploidy from 1.9 to 9.7) not found in the pre-treatment sample." (PMID 38503755, 2024). "Moreover, ERBB2-mediated regulation of PTEN indicates a dual mechanism to promote oncogenesis by upregulating survival pathways while simultaneously downregulating tumor suppressive signals." (PMID 39409883, 2024). "Interestingly, in human breast cancer cell lines, miR-125a act as a tumor suppressor and is underexpressed, interfering with the expression of ERBB2, ERBB3 and HUR (an RNA binding protein), promoting antiproliferative effects." (PMID 38954129, 2024). "Molecular-targeted therapy has recently begun to be used for SGTCs, and druggable molecular targets in SDC specifically include the androgen receptor, ErbB2/HER-2, BRAF, tumor mutation burden, and NTRK gene-fusion, seen in ≥ 80% of salivary gland secretary carcinomas." (PMID 38492066, 2024). "Differences in the effect of dual ERBB2/HER2 blockade and robustness of the association of pCR with EFS could be partly explained by differences in tumor and microenvironment biology." (PMID 38546612, 2024). "It would also be interesting to compare these results with matched tumor samples NGS analyses for patients found negative for ERBB2 mutation on cfDNA samples (which has not been done for economic reasons)." (PMID 38287892, 2024). "ERBB2‐amplified ILBC had higher tumor stage (p < 0.0001), more frequent positive nodal status (p = 0.00022), more distant metastases (p = 0.012), and higher histological grade (p < 0.0001), and were more often hormone receptor negative (p < 0.001) and more often SOX10 positive (p = 0.005)." (PMID 38335502, 2024). "One of the RAD51 high ER-negative breast cancer cases was an ERBB2-positive tumor." (PMID 38648056, 2024). "Genomic analysis of co-existing tumor lineages provides a unique window into the evolutionary dynamics of tumor drug resistance, and can help identify high- confidence resistance mechanisms, as we did here for ERBB2 activation and like prior work has done for various targeted therapies." (PMID 38503755, 2024). "ERBB2 is a known oncogene with significant role in mediating tumor immune response." (PMID 38360850, 2024). "Anticipating the development of such BsAbs, targeting both EGFR and ERBB2 signaling pathways could not only synergistically inhibit tumor growth and enhance anticancer efficacy, but also effectively prevent resistance caused by mutations in either target." (PMID 38713378, 2024). "Furthermore, studies have reported that FGFR3 and MYC overexpression led to an increase in Tregs, inducing an immunosuppressive tumor microenvironment (TME), while ERBB2 overexpression was linked to a decrease in Tregs." (PMID 39410541, 2024). "β-catenin cascade can induce tumor formation through ErbB2 and make cells cancerous." (PMID 37505298, 2024). "Given the observed association of activating ERBB2 and BRAF mutations with RTK/MAPK pathway transcriptional signature, we hypothesized this association could be related to the PAM50 subtype of these tumor samples." (PMID 38503755, 2024).